SOD2 (superoxide dismutase 2)
Diseases named in the same sentence as SOD2 in open-access papers (continued):
Sharing a sentence is not in itself a finding about the gene and the disease.
vitiligo (9 papers, 2013 to 2025). Generalized well circumscribed patches of leukoderma that are generally distributed over symmetric body locations and is due to autoimmune destruction of melanocytes. "The SOD2 Thr58Ile (rs35289490) and Leu84Phe (rs11575993) polymorphisms were significantly associated with vitiligo patients, and the Val16Ala (rs4880) polymorphism was associated with active vitiligo patients." (PMID 40837363, 2025). "The current study further showed that FA was able to protect melanocytes from oxidative injury by lowering intracellular ROS levels and upregulating HO-1 and SOD2, both of which were reported deficient in vitiligo melanocytes." (PMID 34917229, 2021). "Studies suggest that individuals carrying the Ala allele may have a higher risk of developing vitiligo due to reduced SOD2 activity." (PMID 40837363, 2025). "At the protein level vitiligo and healthy melanocytes showed similar staining intensity for catalase, whereas SOD2 labeling was slightly lower in vitiligo cells." (PMID 23555779, 2013). "Superoxide dismutase 2 (SOD2), a mitochondrial form of SODs that converts O2− radicals into H2O2, has shown increasing activity in vitiligo patients, indicating its role as a genetic risk factor for susceptibility and progression of vitiligo." (PMID 36980277, 2023). "Not much data is available about the role of the SOD2 C2734T, but an earlier research had showed that the SNP influenced susceptibility to vitiligo, a skin phenomenon characterized by long-term patches on the skin and loss of skin colour." (PMID 28512644, 2017). "Recently, we have shown that SOD2 and SOD3 polymorphisms may be genetic risk factors for susceptibility and progression of vitiligo and contribute to increased transcript levels and activity of SOD2 and SOD3 in patients." (PMID 24312346, 2013). "In melanocytes isolated from vitiligo patients we observed chronic activation of Nrf2, manganese superoxide dismutase 2 (SOD2), hemeoxigenase-1 (HO-1), NAD(P)H deydrogenase quinone-1 (NQO1) and catalase genes expression that indicated a compromised redox homeostasis." (PMID 23555779, 2013). "Interestingly, our recent study suggests increased levels of SOD2 transcripts and SOD2 activity in vitiligo patients which might be one of the consequences of increased IL1B." (PMID 25221996, 2014). "Moreover, IL1B is a potent activator of superoxide dismutase 2 (SOD2) in different tissues and cell types; which could lead to increased H2O2 production as observed in vitiligo patients." (PMID 25221996, 2014).
amyotrophic lateral sclerosis (8 papers, 2017 to 2025). Amyotrophic lateral sclerosis (ALS) is a neurodegenerative disease characterized by progressive muscular paralysis reflecting degeneration of motor neurons in the primary motor cortex, corticospinal tracts, brainstem and spinal cord. "Mutations in SOD2 can lead to amyotrophic lateral sclerosis (ALS), a neurodegenerative disease." (PMID 40644533, 2025). "Zn-superoxide dismutase (SOD-1), which is mainly related to amyotrophic lateral sclerosis, and Mn-superoxide dismutase (SOD-2) gene expression are induced by ATRA and are mitochondrial-localized antioxidant enzymes." (PMID 38572181, 2024). "Moreover, unlike SOD2(-/-) mice, homozygous mutations in the SOD1 gene are not lethal; still, SOD1(-/-) mice exhibit subtle defects, including Amyotrophic Lateral Sclerosis (ALS), retinal dysfunction, and muscle atrophy." (PMID 33613826, 2021).
Arrhythmia (8 papers, 2012 to 2025). Any cardiac rhythm other than the normal sinus rhythm. "Compared to other studies, we are the first to demonstrate that SOD2 deficiency plays a causal role in arrhythmia." (PMID 41462644, 2025). "The risk of dyspnea or arrhythmia development was assessed via multivariate analysis with respect to SOD2, GPX1, GPX3 and Nrf2 genotypes (respectively)." (PMID 37373377, 2023). "This supports our results that SOD2 KD shows increased CaT loss and contractile dysfunction compared to SOD1 in iAMS and only SOD2 KD, but not SOD1 KD, induced arrhythmia in Drosophila." (PMID 41462644, 2025). "Interestingly, SOD2, but not SOD1, heart-specific and whole-body knockdown increased arrhythmia, validating the in vitro finding that MitoOxS specifically induces cardiac dysfunction." (PMID 41462644, 2025).
endometriosis (8 papers, 2018 to 2025). The growth of functional endometrial tissue in anatomic sites outside the uterine body. "Cases of endometriosis have a relative deficiency of cytodifferentiation enzymes and antioxidant defences (SOD2/PRDXs), correlating with elevated oxidative stress." (PMID 41296460, 2025). "In contrast, an increase in the ratio of SOD2 over GPx1 corresponds to cell proliferation and metastasis whereas the ratio of SOD2/GPx1 is significantly increased in lesion of ectopic endometriosis." (PMID 37968795, 2024). "Moreover, the correlation observed between elevated SIRT3 and SOD2 levels further supports the idea of a coordinated antioxidant response in severe endometriosis, potentially mitigating oxidative stress despite the disease’s severity." (PMID 41009667, 2025). "Although a statistically nonsignificant decrease in SOD2 was found in the samples of the endometriosis group (0.017 ± 0.003) compared with the control group (0.030 ± 0.006), SOD2 levels were significantly increased (P = 0.0006) in the samples of the endometrial cancer group (0.120 ± 0.023)." (PMID 37968795, 2024). "It has been reported that ERβ plays an important role in EMS pathogenesis by modulating its target genes, including NRF1, SOD2, COX2, and MMP1, and specific ERβ suppression, such as ERβ antagonist, has been used for treatment of endometriosis, but with many of limitations and side effects." (PMID 33362719, 2020). "Accordingly, the ratio of SOD2/GPx1 was found to be nonsignificantly elevated in the group of endometrial cancer (0.234 ± 0.061) compared with the control group (0.102 ± 0.032) and slightly decreased in the patients of endometriosis (0.0079 ± 0.022)." (PMID 37968795, 2024).
periodontitis (8 papers, 2019 to 2025). An acute or chronic inflammatory process that affects the tissues that surround and support the teeth. "SOD2, a mitochondrial anti-apoptotic and antioxidant enzyme, exhibits an increased expression in gingival tissues of patients with gingivitis and periodontitis compared with healthy individuals." (PMID 40426961, 2025). "(H) Hematoxylin and eosin (H&E) image and representative spatial mapping of CD81 and SOD2 in healthy and periodontitis gingiva from public dataset GSE206621." (PMID 40801798, 2025). "Then, gingival biopsies from periodontally healthy and periodontitis subjects were also studied for the presence of SOD2 and BIRC3 by immunohistochemistry." (PMID 33435582, 2021). "Gingiva from periodontitis patients showed significantly higher SOD2, BIRC3, CASP3, and CASP9 levels than periodontally healthy gingiva." (PMID 33435582, 2021). "Co-localization in CD81 and SOD2, a neutrophil marker, was found in the periodontitis gingiva." (PMID 40801798, 2025). "Interestingly, spatial transcriptomic analysis of gingival tissue revealed that the regions expressing CD81 and SOD2, a neutrophil marker, in periodontitis overlapped in the gingival lamina propria, showing a high spatial correlation." (PMID 40801798, 2025). "The aim of the study was to clarify whether orthodontic forces and periodontitis interact with respect to the anti-apoptotic molecules superoxide dismutase 2 (SOD2) and baculoviral IAP repeat-containing protein 3 (BIRC3)." (PMID 33435582, 2021). "The present in-vitro and in-vivo study was therefore designed to clarify whether orthodontic forces and periodontitis interact with respect to the regulation of the two anti-apoptotic molecules SOD2 and BIRC3." (PMID 33435582, 2021). "SOD2, a main antioxidant enzyme, could maintain ROS homeostasis under inflammatory conditions and is upregulated in periodontitis." (PMID 31608279, 2019). "Therefore, the upregulation of SOD2 in periodontitis may contribute to the persistence of the inflammatory cellular infiltrate and, consequently, the progression of this inflammatory disease." (PMID 40426961, 2025). "Additionally, in inflammatory environments like periodontitis, it was shown that the expression of NLRP3 inflammasome components is enhanced in response to deficient SOD2 activity, while caspase-1-IL-1β axis is also magnified, suggesting that SOD2 plays a protective role under inflammatory stimuli." (PMID 39329909, 2024). "In addition, a SOD2 increase has also been found in gingival tissues from periodontitis patients." (PMID 33435582, 2021). "However, when these sites were also affected by experimental orthodontic tooth movement, the periodontitis-induced upregulation of SOD2 and BIRC3 was significantly (p < 0.05) reduced again, demonstrating an inhibitory effect of orthodontic forces on these molecules in periodontal infection." (PMID 33435582, 2021). "Previous studies have reported elevated gene expression and protein levels of SOD2 and BIRC3 in patients with periodontitis compared to healthy individuals, suggesting their pivotal role in periodontal infection and inflammation." (PMID 39493178, 2024). "As evidenced by real-time PCR, the transcriptional levels of SOD2 and BIRC3 were significantly (p < 0.05) elevated at gingival sites of experimental periodontitis." (PMID 33435582, 2021). "The quantitative real-time PCR analysis revealed significantly (p < 0.05) increased SOD2 and BIRC3 levels in gingival biopsies of periodontitis patients as compared to gingival samples from periodontally healthy individuals." (PMID 33435582, 2021). "SOD2 and BIRC3 were also studied in gingiva from rats with experimental periodontitis and/or orthodontic tooth movement." (PMID 33435582, 2021). "SOD2 and BIRC3 expressions were also significantly increased in the gingiva from rats with experimental periodontitis, but the upregulation of both molecules was significantly diminished in the concomitant presence of orthodontic tooth movement." (PMID 33435582, 2021).
periodontitis (continued). "First, we analyzed the SOD2 and BIRC3 gene expressions in gingiva of periodontally healthy and periodontitis subjects." (PMID 33435582, 2021). "Our investigation revealed higher SOD2 and BIRC3 gene expression and protein levels in gingiva from periodontitis patients as compared to periodontally healthy gingiva, suggesting a critical role of these molecules in periodontal infection and inflammation." (PMID 33435582, 2021). "SOD2, BIRC3, and the apoptotic markers caspases 3 (CASP3) and 9 (CASP9) were analyzed in gingiva from periodontally healthy and periodontitis subjects by real-time PCR and immunohistochemistry." (PMID 33435582, 2021). "In our study, the upregulation of SOD2 and BIRC3 in human gingiva due to periodontal infection and thereby inflammation was confirmed using an animal model with experimental periodontitis and an in-vitro study on periodontal fibroblasts." (PMID 33435582, 2021). "Since SOD2 and BIRC3 can inhibit apoptosis, we additionally investigated the levels of the apoptotic markers CASP3 and CASP9 in gingival biopsies from periodontally healthy and periodontitis subjects." (PMID 33435582, 2021). "Interestingly, the effect of F. nucleatum on the SOD2 and BIRC3 levels was similar to the actions of clinical periodontal infection, confirming the important etiological role of F. nucleatum in periodontitis." (PMID 33435582, 2021).
psoriasis (8 papers, 2011 to 2024). An autoimmune condition characterized by red, well-delineated plaques with silvery scales that are usually on the extensor surfaces and scalp. "Deficiencies or dysregulation of SOD activity, particularly SOD2, leads to increased mtROS and oxidative stress, which have been associated with various diseases and conditions, including psoriasis." (PMID 39456475, 2024). "No notable disparities were detected in the manifestation of SOD1 or SOD2 genes among patients and controls, as well as across various clinical subtypes of psoriasis." (PMID 39456475, 2024). "In terms of psoriasis, SOD2 functioned as a regulator in psoriatic macrophages, resulting in enhanced presence of mitochondrial ROS." (PMID 36890558, 2023). "The SOD2 expression level is decreased in multiple diseases, including cancer, neurodegenerative diseases, and psoriasis." (PMID 32117613, 2020). "The SOD2 rs4880 variant, described either as a missense mutation (Val16Ala) or a change in the regulatory 5′UTR sequence, has been reported to be associated with arthropathic psoriasis." (PMID 38791044, 2024). "Five potential hub genes of psoriasis were obtained, including SOD2, PGD, PPIF, GYS1 and AHCY." (PMID 36890558, 2023). "The only result that was of note was the observation that blood selenium levels were significantly lower for carriers of the CC variant of SOD2, CAT, and DMGDH, which may be a generalized effect of these polymorphisms and the association between Se and psoriasis." (PMID 38791044, 2024). "Then, 5 potential hub genes (SOD2, PGD, PPIF, GYS1, AHCY) of psoriasis were identified by protein–protein interaction (PPI) networks using Metascape database." (PMID 36890558, 2023). "Together, the 5 hub genes (SOD2, PGD, PPIF, GYS1 and AHCY) play pivotal roles in the development of psoriasis." (PMID 36890558, 2023). "The elevated expression of SOD2 in skin lesions and the plasma activity of SOD were observed in patients with psoriasis that was assumed to be a protective response against oxidative stress." (PMID 36890558, 2023). "We found that SOD2, PGD, PPIF, GYS1 and AHCY are five hub genes in PPI networks, indicating the potential role in the psoriasis initiation and progression." (PMID 36890558, 2023).
renal carcinoma (8 papers, 2014 to 2022). A carcinoma arising from the epithelium of the renal parenchyma or the renal pelvis. "While thought to be a strict mitochondrial protein, SOD2 has been recently reported to be secreted in renal carcinoma." (PMID 36010852, 2022). "We observed that sorafenib treatment decreased SOD-2 expression in renal cancer cells compared with control, while c-Met activation markedly restored SOD-2 in sorafenib-treated cells." (PMID 30647407, 2019). "Among the most altered genes, it has been shown that renal cancer progression can be promoted by upregulation of CXCL8, ADAM9, NDRG1, SOD2, SREBF1 and SREBF2 genes." (PMID 35505422, 2022). "Interestingly, SOD2 expression has also been shown to be suppressed under hypoxia in renal carcinoma cells in a HIF-1 dependent manner, suggesting that SOD2 expression under hypoxia is context-specific, and may represent one of the opposing facets of HIF-1 and HIF-2 activity." (PMID 30767037, 2019). "Besides glutathione synthesis deregulation, antioxidant enzymes such as superoxide dismutase 2 (SOD2) and glutathione peroxidase (GP3) are frequently inactivated by promoter hypermethylation in lung and renal cancer, respectively." (PMID 28931650, 2017).
retinal degeneration (8 papers, 2016 to 2024). Degeneration of the retina. "RPE oxidative stress-mediated retinal degeneration was induced by exon specific deletion of the protective enzyme MnSOD (encoded by Sod2) by cre/lox mechanism." (PMID 34070383, 2021). "A positive correlation between SOD2 deficiency and the development of retinal degeneration has also been demonstrated previously." (PMID 32344885, 2020). "EPO-R76E over-expression in RPE delayed the retinal degeneration as measured by light microscopy in RPE specific Sod2 knockout mice." (PMID 34070383, 2021). "Overexpressing SOD2 in glial cells of the ADAM17−/− retinas also led to a significant rescue of retinal degeneration." (PMID 32715522, 2020). "For another mouse model of retinal degeneration, where RPE damage was induced by deletion of Superoxide Dismutase 2 (Sod2), it was reported that the damage to the RPE cells precedes and induces PR loss." (PMID 34827622, 2021). "It would be of interest to study whether this prodrug will be applicable to prevent retinal degeneration in animal models, specifically those that exhibit elevated oxidative stress in the RPE monolayer (for example, in Sod2 knockout mice)." (PMID 33923192, 2021). "We found that early replacement of Sod2 in RPE delayed retinal degeneration, whereas replacement of Sod2 after substantial RPE damage had already occurred did not prove effective, suggesting that antioxidant gene therapy may be useful as a preventive but not as a therapy for GA." (PMID 28241311, 2017).
acute kidney injury (7 papers, 2020 to 2024). Sudden and sustained deterioration of the kidney function characterized by decreased glomerular filtration rate, increased serum creatinine or oliguria. "Melatonin relieves contrast-induced acute kidney injury by activating SIRT3 and diminishing ac-SOD2 K68, thus exerting an antioxidative effect." (PMID 35372451, 2022). "In a mouse model of acute kidney injury, SIRT3 reduced Ac-SOD2 and ROS levels and attenuated oxidative damage, thereby resisting apoptosis." (PMID 34869361, 2021). "In this regard, it has been shown that the conditional deletion of FOXO3 exacerbates acute kidney injury (AKI) to CKD transition by reducing epithelial autophagy and lowering SOD2 expression." (PMID 34291592, 2021).
brain injury (7 papers, 2010 to 2025). Acute and chronic (see also brain INJURIES, CHRONIC) injuries to the brain, including the cerebral hemispheres, CEREBELLUM, and brain STEM. "Oxidative stress played fundamental role in the pathogenesis of ischemic brain injury, and SOD2 gene polymorphism might contribute to individual variability in oxidative stress status." (PMID 34790286, 2021). "Studies have shown that the overexpression of SOD2 can protect mesenchymal stem cells in the brain and improve the recovery of neural inflammation and brain injury in traumatic brain injury mice." (PMID 40070041, 2025). "Regarding the 2-month-old SOD2+/−, we have observed a decrease in the total response compared to WT control animals and an even stronger decrease in the SOD2+/− mice subjected to brain trauma." (PMID 34679709, 2021). "On the contrary, the group of SOD2+/− animals subjected to brain trauma have an increase of more than 100% in their expression levels." (PMID 34679709, 2021). "We evaluated the cognitive performance of WT and SOD2+/− mice subjected to brain trauma." (PMID 34679709, 2021). "However, the phospho-tyrosine 1472 label decreases by 20% in the SOD2+/− control animals and drops further by about 50% (49.7 ± 10.5) in the same animals subjected to brain trauma." (PMID 34679709, 2021). "In conclusion, the results of this study imply that application of HBOT, via altering SOD2 ‎expression, may attenuate imbalance between oxidants and antioxidants that occurs after brain ‎injury, and in that way contributes to the maintenance of pro-/antioxidant homeostasis." (PMID 23275324, 2012). "In contrast, the SOD2+/− animals subjected to brain trauma do not present a significant difference in the preference index, and they are significantly different from the control group for the novel object indicating a cognitive failure in this experimental group." (PMID 34679709, 2021).
brain tumor (7 papers, 1996 to 2025). "Although knowledge about SOD2 in brain tumours is limited, recent studies suggest that reduced SOD2 levels correlate with lower tumour proliferation and longer survival in TMZ‐resistant GBM models." (PMID 39866010, 2025). "Among them, the Ala variant of SOD2 rs4880 and the C variant of SOD3 rs699473 are found to be associated with brain tumor risk." (PMID 36307808, 2022). "Single nucleotide polymorphisms of OS-responsive genes, such as CAT, SOD1, SOD2, SOD3, GPx1, NOS3, and PON1 have been found in adult brain tumor studies." (PMID 36307808, 2022). "Thus, the pharmacological or genetic activation of SOD2 and SOD3 could mitigate the risk of brain tumors." (PMID 36307808, 2022).